PCSK9 (proprotein convertase subtilisin/kexin type 9)
Diseases named in the same sentence as PCSK9 in open-access papers (continued):
Sharing a sentence is not in itself a finding about the gene and the disease.
Hepatic steatosis (continued). "In animal models, berberine attenuates atherosclerotic lesions and hepatic steatosis by downregulating PCSK9 expression, further supporting its role in cardiovascular protection." (PMID 40764605, 2025). "This underscores the multifaceted nature of PCSK9 involvement in critical biological processes related to liver steatosis." (PMID 39683393, 2024). "For example, PCSK9 rs11591147 (p.R46L) LOF has a protective effect on hepatic steatosis, NAFLD/NASH, and fibrosis." (PMID 38344397, 2024). "Clinical and pre-clinical evidence suggests a relationship between PCSK9 expression and hepatic steatosis." (PMID 37242292, 2023). "PCSK9 knockout (KO) mice develop severe hepatic steatosis when fed a high-fat diet, since PCSK9 reduces the expression of fatty acid translocase also known as CD36, a scavenger receptor for fatty acid uptake and the main driver of their uptake in the liver." (PMID 35900635, 2022). "Circulating PCSK9 levels were elevated in patients with histologically proven liver steatosis, and a positive correlation with the hepatic expression of genes involved in de novo lipogenesis, necroinflammation and fibrosis stages were identified." (PMID 35162992, 2022). "Feeding male PCSK9 KO mice a high-fat diet for 6 weeks worsened hepatic steatosis, inflammation and fibrosis." (PMID 35162992, 2022). "In a cohort of 29 patients, ALT levels and radiologically diagnosed liver steatosis improved in 8 out of 11 patients after PCSK9 antibody treatment for ~2 years." (PMID 35162992, 2022). "A study of 201 patients showed a positive correlation between circulating PCSK9 and hepatic steatosis grade." (PMID 35323699, 2022). "In morbidly obese patients, hepatic PCSK9 expression is inversely correlated with hepatic fat accumulation, while circulating PCSK9 levels correlate with the severity of liver steatosis." (PMID 35323658, 2022). "This study also observed that plasma PCSK9 concentrations were related to liver steatosis, as judged by ultrasound." (PMID 35162992, 2022). "For example, it was shown that PCSK9 knockout mice develop hepatic steatosis after high-fat diet related to increased expression of CD36 on hepatocytes." (PMID 35050192, 2022). "High fat diet (HFD) feeding was shown to induce hepatic steatosis and increase circulating as well as hepatic PCSK9 levels in mice." (PMID 35323658, 2022). "In patients with moderate and severe hepatic steatosis (grade 2 and 3 steatosis), AG + GG genotypes of PCSK9 rs505151 were more prevalent than AA genotype (OR 8.667; 95% CI 1.841–40.879; P value = 0.004) compared to patients with mild steatosis (grade 1)." (PMID 34876018, 2021). "Although, PCSK9 and PCSK7 can theoretically be associated with hepatic steatosis there is few clinical studies in this regard." (PMID 34876018, 2021). "In patients with moderate to severe hepatic steatosis, AG + GG genotypes of PCSK9 rs505151 were more prevalent compared to AA genotype (OR 8.667; 95% CI 1.841–40.879; P value = 0.004)." (PMID 34876018, 2021). "Recently, it has been shown that hepatic steatosis following HFD results in the induction of liver PCSK9 mRNA and protein, a process involving saturated FA-induced, SREBP2-driven de novo PCSK9 expression." (PMID 33643060, 2021). "In conclusion, we have shown that pharmacological inhibition of PAI-1 prevents hepatic steatosis and reduces serum cholesterol levels through a mechanism that involves reduced PCSK9 synthesis." (PMID 33432099, 2021). "We also assessed the regulation of hepatic steatosis by sauchinone in vivo and the proposed genes including PCSK9 and SREBP-2." (PMID 29712938, 2018). "Likewise, in 13 patients with heterozygous familial hyperlipidemia and NAFLD, inhibition of PCSK9 improved hepatic steatosis, inflammation and fibrosis." (PMID 35162992, 2022).
Hepatic steatosis (continued). "Furthermore, given recent studies showing that serum PCSK9s areinvolved in the pathogenesis of hepatic steatosis and alcohol-inducedinflammation, PCSK9 inhibitors are increasingly utilized and expected toplay a protective role in liver diseases." (PMID 39076187, 2022). "Of note, blockage of PCSK9 in dyslipidemic patients improved hepatic steatosis and may prevent NASH." (PMID 35162992, 2022). "Furthermore, in another study with 698 participants, it was demonstrated that circulating PCSK9 levels were firmly related to all plasma biomarkers of liver function and the presence of hepatic steatosis." (PMID 35323699, 2022). "In addition, a clinical study enrolled 201 patients undergoing liver biopsy for suspected NAFLD, examined the relation of PCSK9 with liver damage and showed that circulating concentration of PCSK9 was significantly related to liver steatosis grade (P = 0.012)." (PMID 34996457, 2022). "Although positive correlations of circulating PCSK9 with hepatic steatosis and markers of liver injury existed in some cohorts such associations could not be identified in other studies." (PMID 33461570, 2021). "Thus, it is evident that sauchinone reduces hepatic steatosis by downregulating the expression of hepatic PCSK9 via SREBP-2." (PMID 29712938, 2018). "Moreover, PCSK9(−/−) mice showed impairment of liver regeneration, while PCSK9(+/−) mice exhibit an improved liver regeneration and resistance to hepatic steatosis; this finding indicates that a moderate level of the PCSK9 protein can protect mice against MAFLD and MASH." (PMID 39963241, 2025). "PCSK9 inhibitors may reduce liver steatosis, inflammation, and fibrosis." (PMID 40142198, 2025). "As a PCSK9 inhibitor, sauchinone could be of interest to treat fatty liver disease." (PMID 40333626, 2025). "PCSK9 may also be involved in the pathogenesis of fatty liver disease." (PMID 38344397, 2024). "In addition to a reduction in diet-induced hepatic steatosis and adiposity, Our results also show that in addition to its hepato-protective effect, the ME improved a pro-atherogenic serum profile by lowering circulating PCSK9 and ApoB." (PMID 37242292, 2023). "Therefore, PCSK9 is thought to mitigate various mechanisms of hepatic steatosis and liver injury." (PMID 37242292, 2023). "Thus, the effects of PCSK9 in olanzapine-related hepatic steatosis may be mediated via the upregulation of FAS and SCD1." (PMID 35379885, 2022). "Moreover, PCSK9 can protect against hepatic steatosis in the presence of excess dietary fats." (PMID 35024053, 2021). "Additionally, we found that PCSK9 is associated with liver steatosis upon HFruc diet, without any correlation with IMCL." (PMID 23298392, 2013). "Suppression of FAF2 expression alleviated alcohol-induced liver steatosis through ATGL activation and SREBP1 pathway, as well as reducing plasma LDL levels via the PCSK9 pathway." (PMID 39969435, 2025). "The PCSK9 inhibitor acts instead by modulating both the internalization of the LDL receptor at the liver level, but also by improving hepatic steatosis." (PMID 38567250, 2024). "We conducted this study to explore the association between genetic variations in TM6SF2 rs58542926, PCSK9 rs505151 and PCSK7 rs2277287 and hepatic steatosis in liver transplant recipients." (PMID 34876018, 2021). "The collective results implicate sauchinone as being potentially valuable in the treatment of hepatic steatosis, as it inhibits PCSK9 induction and HFD-induced hepatic steatosis." (PMID 29712938, 2018). "Our study demonstrated that Faf2 knockdown significantly reduced PCSK9 expression at both mRNA and protein levels, indicating that FAF2 may regulate PCSK9 expression and, thus, play a critical role in the development of liver steatosis." (PMID 39969435, 2025).
Hepatic steatosis (continued). "In humans, it has been concluded that the severity of hepatic steatosis affects the correlation between circulating PCSK9 and liver fat content, with a possible impact of circulating PCSK9 in the early stages of NAFLD, but not in the late stages." (PMID 36983739, 2023). "Serum PCSK9 was not induced in HCV patients with liver steatosis but was higher in patients with metabolic fatty liver." (PMID 33920491, 2021). "The PCSK9-deficient mice exhibited less lipid accumulation in hepatocytes, thus indicating that the lack of PCSK9 prevents development of hepatic steatosis." (PMID 26674961, 2015). "Serum PCSK9 levels were not changed in patients having the fatty liver disease." (PMID 33920491, 2021).
ischemic stroke (44 papers, 2007 to 2026). A stroke disorder caused by obstruction of blood flow to the brain, due to thrombotic (local blood clot formation) or embolic (due to a blood clot or other material traveling from another site) event. "Clinical trials such as FOURIER and ODYSSEY OUTCOMES have demonstrated a noteworthy decrease in the risk of cerebrovascular diseases, encompassing ischemic stroke and recurrent ischemic stroke, through the administration of PCSK9 inhibitors." (PMID 41601579, 2026). "In high-risk cardiovascular disease patients, the administration of PCSK9 inhibitors demonstrated a noteworthy decrease in the risk of cerebrovascular diseases, encompassing ischemic stroke and recurrent ischemic stroke." (PMID 41601579, 2026). "In a 2020 MR analysis, genetically elevated LDL-C and apoB were specifically tied to increased risk of large-artery stroke (LAS), while PCSK9-mediated LDL-C reduction showed protective effects across all ischemic stroke types." (PMID 40863347, 2025). "A meta-analysis comprising 16 RCTs revealed a noteworthy 23% reduction in the risk of ischemic stroke after using PCSK9 inhibitors." (PMID 39767636, 2024). "This article aims to provide a comprehensive review, encompassing the association between PCSK9 and the heightened risk of ischemic stroke, the mechanisms, and the extensive evidence supporting the proven efficacy of PCSK9 inhibitors in clinical practice." (PMID 38273837, 2023). "Several recent trials have shown that PCSK9 inhibitors reduce platelet activity and that thrombosis significantly reduces the risk of ischemic stroke." (PMID 38273837, 2023). "Comparing the association of PCSK9 GS with hemorrhagic and ischemic stroke indicated the GS had a differential effect (p-value = 0.02)." (PMID 31664920, 2019). "With regards to the association of disease, this meta-analysis revealed that the co-dominant model of PCSK9 rs505151 is associated with ischemic stroke, where the distribution of G allele is higher among ischemic stroke patients." (PMID 26666837, 2015). "For the PCSK9 rs505151 polymorphism, the OR of co-dominant model (OR = 1.36, 95% CI:1.01–1.58) was found to be higher among ischemic stroke patients." (PMID 26666837, 2015). "Within the PCSK9 region, among women with the AA genotype for SNPs rs630431 or rs568052 the risk of ischemic stroke was approximately doubled by E-alone; in contrast, risk elevations of a similar magnitude by E+P were noted among women with the GG genotype." (PMID 22794791, 2012). "PCSK9 inhibitors have demonstrated efficacy to reduce the risk of ischemic stroke." (PMID 40354375, 2025). "In conclusion, the current meta-analysis suggested that the variant alleles of OLR1 rs11053646 and PCSK9 rs505151 may confer an increased risk of ischemic stroke." (PMID 26666837, 2015). "Thus far, no meta-analysis has yet been conducted to investigate the relationship between OLR1 rs11053646 and PCSK9 rs505151 polymorphisms and ischemic stroke." (PMID 26666837, 2015). "In conclusion, the current meta-analysis highlighted that variant allele of OLR1 rs11053646 G > C and PCSK9 rs505151 A > G may contribute to the susceptibility risk of ischemic stroke." (PMID 26666837, 2015). "We studied whether the PCSK9 gene is linked to the risk of ischemic stroke (IS) and with the development of intracranial atherosclerosis." (PMID 17940607, 2007).
ischemic stroke (continued). "PCSK9-GS was associated with lower risks of carotid plaque [n = 8340 cases; OR = 0.61 (95% confidence interval: 0.45–0.83); P = 0.0015], major occlusive vascular events [n = 15 752; 0.80 (0.67–0.95); P = 0.011], and ischaemic stroke [n = 11 467; 0.80 (0.66–0.98); P = 0.029]." (PMID 38198221, 2024). "Similarly, a meta-analysis of 39 randomized controlled trialsincluding 66,478 patients indicated that PCSK9 inhibitors lowered the risk of MIby 20% (95% CI, 14–26%; p< 0.0001), ischemic stroke by 22% (95%CI, 11–33%; p = 0.0005) and coronary revascularization by 17% (95%CI, 11–22%; p< 0.0001)." (PMID 39076402, 2023). "However, there is limited evidence that PCSK9 variants are associated with ischaemic stroke (IS)." (PMID 29020353, 2018). "This review seeks to synthesize contemporary evidence on the therapeutic potential of PCSK9 inhibition in ischemic stroke, spanning from molecular mechanisms to clinical applications." (PMID 41190281, 2025). "With ongoing research into novel formulations (e.g., oral PCSK9‐i, siRNA therapies) and biomarker‐guided approaches, PCSK9‐i are poised to become cornerstone therapies in ischemic stroke management." (PMID 41190281, 2025). "As the therapeutic evidence evolves, PCSK9‐i demonstrate significant potential as an adjunctive or alternative therapeutic strategy in the secondary prevention of ischemic stroke." (PMID 41190281, 2025). "PCSK9‐i have demonstrated significant therapeutic potential across the spectrum of ischemic stroke management, encompassing primary prevention, secondary prevention, acute‐phase treatment, and long‐term prognosis improvement." (PMID 41190281, 2025). "For instance, loss-of-function variants in PCSK9, such as rs11591147, have been shown to lower LDL-C levels and are associated with a reduced risk of ischemic stroke." (PMID 40863347, 2025). "We provided theoretical evidence to explore the application of PCSK9 inhibitor to prevent carotid plaque rupture, so as to decrease the incidence of ischemic stroke." (PMID 38402551, 2024). "We sought to provide clues and evidence for stabilizing carotid plaques and decreasing the incidence of ischemic stroke, so as to expand the application of PCSK9 inhibitors." (PMID 38402551, 2024). "Studies have revealed that patients with gain-of-function PCSK9 variants have a higher LDL-C and an increased risk of ischemic stroke." (PMID 37528862, 2023). "In recent years, a great breakthrough in ischemic stroke treatment has been witnessed with the emergence and use of a novel lipid-lowering medication, Proprotein convertase subtilisin kexin type 9 (PCSK9) inhibitor." (PMID 38273837, 2023). "Through this present study, we can gain deeper insights into the utilization and impact of PCSK9 inhibitors in treating ischemic stroke." (PMID 38273837, 2023). "The mechanism of increased platelet activity of PCSK9 is not yet fully understood, and more trials can be conducted to further understand the mechanism in order to improve PCSK9 inhibitors and make them more targeted in the treatment of ischemic stroke." (PMID 38273837, 2023). "In the future, we should also conduct clinical trials of PCSK9 inhibitors in patients with TIA (disease events prone to progression to ischemic stroke) to develop their broader adaptation." (PMID 38273837, 2023). "An obvious detrimental role for PCSK9 on brain health is by increasing LDL-C levels which accelerates intracranial atherosclerosis (in particular of large vessels) leading to ischemic strokes." (PMID 37586604, 2023). "Previous MR studies have showed a weaker effect on ischemic stroke than on CAD for some lipid metabolic factors, such as low-density lipoprotein cholesterol and proprotein convertase subtilisin/kexin type 9 (PCSK9) variants." (PMID 35859596, 2022).